RAB6C (RAB6C, member RAS oncogene family)
Description:
The small GTPases Rab are key regulators of intracellular membrane trafficking, from the formation of transport vesicles to their fusion with membranes. Rabs cycle between an inactive GDP-bound form and an active GTP-bound form that is able to recruit to membranes different sets of downstream effectors directly responsible for vesicle formation, movement, tethering and fusion (By similarity). RAB6C may be involved in the regulation of centrosome duplication and cell cycle progression.
Synonyms: WTH3
Tractability: PROTAC: ubiquitination databases record sites on it.
Gene: Protein-coding gene on chromosome 2 (129,979,666 to 129,982,738, forward strand). Ensembl gene ENSG00000222014.
Subcellular location: Nucleus; Cytoplasm; Cytoplasm, cytoskeleton, microtubule organizing center, centrosome
Subcellular location (Human Protein Atlas): Golgi apparatus; Basal body
Gene Ontology:
Molecular function: GTPase activity; protein binding; G protein activity; GTP binding
Biological process: mitotic cell cycle; regulation of centrosome duplication; response to xenobiotic stimulus; intra-Golgi vesicle-mediated transport; protein localization to Golgi membrane; retrograde transport, endosome to Golgi; retrograde vesicle-mediated transport, Golgi to endoplasmic reticulum; small GTPase-mediated signal transduction
Cellular component: centrosome; cytoplasm; nucleus; cytosol
Genetic constraint (gnomAD): Loss-of-function variants: 8 observed, 15.64 expected, observed/expected ratio (o/e) 0.51, 90% interval 0.3 to 0.92. The synonymous counts are far from expectation, so gnomAD's model fits this gene poorly and the ratio says little. Missense variants: 151 observed, 271.62 expected, observed/expected ratio (o/e) 0.56, 90% interval 0.49 to 0.64. Synonymous variants: 78 observed, 106.21 expected, observed/expected ratio (o/e) 0.73, 90% interval 0.61 to 0.89.
Homologues: Paralogues in human: RAB6D (99% identical), RAB6A (73% identical), RAB6B (67% identical), RAB41 (48% identical), RAB8B (32% identical), RAB8A (31% identical), RAB5A (30% identical), RAB26 (30% identical), RAB5B (30% identical), RAB5C (30% identical), RAB10 (29% identical), RAB13 (29% identical), and 56 more.
Diseases named in the same sentence as RAB6C in open-access papers:
RAB6C is named in the same sentence as 5 diseases in open-access papers, as found by Europe PMC text mining. Sharing a sentence is not in itself a finding about the gene and the disease. The quoted sentences say what the papers report.
preeclampsia (1 paper, 2023). Preeclampsia is a hypertensive disorder of pregnancy that is characterized by new-onset hypertension with proteinuria presenting after 20 weeks of gestation, and depending on mild or severe forms may initially present with severe headache, visual disturbances, and hyperreflexia. "Characteristic genes, LEP, SASH1, RAB6C, and FLT1 can be used as diagnostic and therapeutic targets for preeclampsia, and they are associated with immune cell infiltration." (PMID 37389124, 2023). "Our findings suggest that LEP, SASH1, RAB6C, and FLT1 can be used as placental markers for preeclampsia and they are associated with various immune cells." (PMID 37389124, 2023). "The expression of LEP in the blood samples of patients with preeclampsia was significantly higher than that in control patients (p = 0.047); the expression of RAB6C was lower in the blood of patients with preeclampsia." (PMID 37389124, 2023). "Finally, RAB6C expression in patients with preeclampsia showed a downward trend in both placental and blood samples." (PMID 37389124, 2023). "In the present study, we screened LEP, FLT1, RAB6C, and SASH1 as potential biomarkers for preeclampsia." (PMID 37389124, 2023). "We identified characteristic genes of preeclampsia as LEP, FLT1, RAB6C, and SASH1 using the GEO database and verified them using the GSE160888 and GSE96985 datasets." (PMID 37389124, 2023). "In summary, LEP, FLT1, RAB6C, and SASH1 were identified as potential biomarkers of preeclampsia." (PMID 37389124, 2023). "However, there are no reports on the relationship between preeclampsia and RAB6C, which may hence be a novel molecule worthy of further study." (PMID 37389124, 2023).
tumor (2 papers, 2010 to 2026). "Genes like DAPK1, LRPPRC, RAB6C, and ZNF471 are found to be the targets of promoter hypermethylation that leads to the altered gene expression patterns that help in growth of tumours." (PMID 41487403, 2026). "The identified genes are involved in drug transport and detoxification (ABCB1, DNAJC15, GSTP1, RAB6C), DNA damage repair (BRCA1) as well as tumor cell proliferation/invasion (APC, CDH1, ESR1, HIC, PLAU, RASSF1, SULF2, TGM2)." (PMID 20544021, 2010).
RAB6C also shares sentences with these, for which no sentence is quoted: breast carcinoma (1 paper); cancer (1); prostate carcinoma (1).